BRAF (B-Raf proto-oncogene, serine/threonine kinase)
Diseases named in the same sentence as BRAF in open-access papers (continued):
Sharing a sentence is not in itself a finding about the gene and the disease.
cancer (continued). "Finally, cell lines partially inhibited by BRAF degradation also contain other oncogenic drivers, making them multi-driver cancer cells." (PMID 38136350, 2023). "This study demonstrated that a proteolysis targeting chimera (PROTAC), SJF-0628, is effective in directing the degradation of BRAF V600E in CRC and TNBC cancer cells, providing a tool to probe the effects of BRAF degradation and inhibition on cell signaling and proliferation." (PMID 38136350, 2023). "Although the presence of a BRAF mutation had no prognostic effect in MSI-H cancer, it was strongly associated with a poorer prognosis in MSS cancer." (PMID 37620872, 2023). "The combination of sotorasib with a type I BRAF inhibitor may enhance sotorasib's drug addiction effect and may provide clinical benefits for patients with cancer." (PMID 37386628, 2023). "Additionally, we show that how the concept of a reaction channel provides an intuitive explanation for resistance to RAF and MEK inhibitors individually and in combination in different BRAF mutant cancers." (PMID 36700386, 2023). "In addition, the combination of MEK inhibitor with BRAF or BCL-XL inhibitors have shown better clinical outcomes in cancer patients than a single drug." (PMID 38001714, 2023). "In Australia, there is currently access to vemurafenib/cobimetinib for adult patients with BRAF-mutant cancers via a national clinical trial platform called the Molecular Screening and Therapeutics Program (MoST): Addendum 12, Substudies 27-30 (ACTRN12620000861954)." (PMID 37124503, 2023). "While AI histology studies have been conducted in humans to detect BRAF mutation in cancer, comparable studies in animals are lacking." (PMID 37570213, 2023). "The assessment of BRAF mutation is obviously less effective in these circumstances, just as it is less effective in the case of category IV BSRTC, where the percentage of PTCs among cancers is often even lower." (PMID 37686562, 2023). "Hence, although the drug addiction phenomenon was noted in KRAS, BRAF, and MEK inhibitor-treated cancers, the underlying mechanisms are different." (PMID 37386628, 2023). "Droplet digital PCR (ddPCR) analysis of the fraction of KRAS/NRAS/BRAF mutated gene copies in kinase-rearranged tumors indicated that there was simultaneous co-occurrence of two activating events in cancer cells, but not genetic mosaicism." (PMID 37686416, 2023). "Pharmacologic activation of the MAPK pathway with a type I BRAF inhibitor could further enhance the effects of sotorasib withdrawal on sotorasib-resistant cancer cells both in vitro and in vivo." (PMID 37386628, 2023). "Moreover, the get-dPCR technique demonstrated the ability to distinguish single-base mutations with extreme clarity, as exemplified in the detection of three cancer mutations, KRAS c.35G > T, BRAF c.1391G > T, and BRAF c.1799T > A." (PMID 37686219, 2023). "Additionally, multiple de novo CTC-exclusive mutations have been identified in genes that are associated with human cancers, namely, KRAS, BRAF, and PIK3CA." (PMID 36980717, 2023). "BRAF mutations are commonly associated with RET/PTC rearrangement and other frequently occurring genetic mutations, and are thought to play an independent role in the development of cancer." (PMID 37370792, 2023). "Although dramatic decreases in the cancer cell metabolism gene signature ensue with combined BRAF/MEK inhibition, indicative of an overall low metabolic activity in MRD, this metabolic signature was decreased to a significantly lesser extent in the CD36+ cells, compared with the CD36– subpopulation." (PMID 37616051, 2023). "Additional genetic alterations in BRAF-mutants are required for cancer development." (PMID 37239381, 2023).
cancer (continued). "Similarly, most of the genes these variants locate on are associated with one (20.86%) or two (55.83%) indications, with exceptional BRAF, ERBB2, KRAS and EGFR associated with >10 types of cancer indications." (PMID 36856726, 2023). "Only one study, including non-metastatic node-positive and node-negative patients, showed an association between BRAF mutations and survival in non-metastatic patients, in which the presence of a BRAF mutation predicted worse cancer-free survival (CFS)." (PMID 37344790, 2023). "Thus, BRAF V600E is an excellent target for developing pharmacological inhibitors and therapeutic interventions in the cancers." (PMID 38136350, 2023). "These cancer cell lines can be considered mono-driver (BRAF V600E) cancer cells." (PMID 38136350, 2023). "While the combination of the analysis of 5′/3′-end RET expression imbalance and variant-specific PCR allowed identification of RET translocations in approximately 2% of consecutive NSCLCs, this estimate approached 120/2361 (5.1%) in EGFR/KRAS/ALK/ROS1/BRAF/MET-negative carcinomas." (PMID 37445709, 2023). "In addition, we will describe the evolving science of molecularly targeted therapies and ICIs for BRAF-dependent cancers." (PMID 35433454, 2022). "As a result, the development of a BRAF antagonist will alter treatment options in cancer treatment from the early to late-stage carcinoma and may aid in overcoming drug resistance." (PMID 36267655, 2022). "In the case of BRAF-mutant cancers, such image-guided considerations may help a clinician weigh trade-offs between related KIs such as encorafenib and dabrafenib." (PMID 35486732, 2022). "lnc-RNA of BRAF could be another mechanism of cancer proliferation and TKI escape in HCC and the inhibition could become a possible strategy treatment for HCC." (PMID 36051249, 2022). "BRAF mutant cancers with wild type PIK3CA had TMB above 200 in 70% of cases." (PMID 36079062, 2022). "BRAF inhibitors act differentially on cancer and healthy cells." (PMID 35494017, 2022). "Cancer cells depend primarily on the gene expression of KRAS or BRAF to survive." (PMID 36245983, 2022). "Aberrant expression of BRAF gene has been demonstrated in various cancer types." (PMID 35910024, 2022). "In this study, we conducted a more comprehensive analysis of BRAF expression in pan-cancer." (PMID 35910024, 2022). "In contrast, for practices where clinical guidelines favor AS, a smaller panel of markers with high PPV for cancer (BRAF V600E single-gene test or seven-gene panel) may suffice for selecting nodules that warrant resection." (PMID 36077677, 2022). "Despite the importance of BRAF mutations in cancer, the clinical associations, genetic interactions and therapeutic implications of non-V600 BRAF mutations have not been explored comprehensively yet." (PMID 36275468, 2022). "A series of novel BRAF-targeting pyrazole-based derivatives developed recently may prove useful against cancer." (PMID 36557840, 2022). "Altogether our findings show that BRAF V600 status plays an important role in regulating the immunomodulatory lipid profile that may offer potential therapeutic benefit and improve patient outcomes for cancers driven by BRAF." (PMID 35565240, 2022). "BRAF mRNA expression was compared across 32 TCGA cancer types and exhibited a relatively consistent trend, suggesting that there may be a common mechanism to promote BRAF expression." (PMID 35910024, 2022). "Furthermore, SET/CIP2A overexpression was frequently observed in cancers with mutations in various oncogenes (e.g., EGFR, KRAS, NRAS, and BRAF)." (PMID 36463234, 2022). "Indeed, oncogenic mutations in BRAF cause up to 30% of all cancers, and small molecule inhibitors of RAF kinases are already in use as anti-cancer drugs." (PMID 36331065, 2022).
cancer (continued). "BCL11A (B-cell lymphoma/leukemia 11A) gene is a cancer gene that encodes the C2H2 zinc finger transcription factor and a component of the BRAF complex, which has been shown to be associated with the regulation of cell proliferation, apoptosis, and transformation." (PMID 36230873, 2022). "BRAF alteration frequency among various cancer types was dramatically different." (PMID 35910024, 2022). "Relapse was also frequently present in several cancers under treatment with BRAF inhibitor." (PMID 35055392, 2022). "BRAF participates in the formation and development of malignant tumors." (PMID 36230547, 2022). "BRAF is a serine/threonine protein kinase representing an oncogenic driver in many human cancers." (PMID 36499450, 2022). "Coinciding with BRAF, ALK has been considered as a driving event in several cancer types due to its mutation and amplification, while the expression of ALK in AML samples and high-risk group is contrarily elevated, making it a risk factor to indicate oncogenesis and poor prognostic." (PMID 36292722, 2022). "Then, we evaluated the correlation between methylation and BRAF expression in pan-cancer." (PMID 35910024, 2022). "The significance and prevalence of the wide spectrum of BRAF gene alterations in cancer is largely unknown." (PMID 35884534, 2022). "BRAF mutant cancers were more commonly MSI high or POLE positive." (PMID 36079062, 2022). "Thus, ACA-28 and/or GT-7 were shown to induce apoptosis in cancer cell lines with different oncogenic mutations, ranging from HER2, BRAF, NRAS, and KRAS." (PMID 35203351, 2022). "By crossing and analyzing different genetic models, we confirm that transcriptional re-activation of TBX3 is an indispensable molecular event for cancer initiation and progression, whereby it links BRAF/MAPK pathway activation to CXCR2 ligands elicited MDSCs infiltration." (PMID 35332119, 2022). "The Ser/Thr kinase BRAF provides an instructive example of how different designs of inhibitors can produce distinct biological outcomes, with important consequences for their application in cancer therapy, reviewed by Ref.." (PMID 35830914, 2022). "RAS or RAS‐like mutation (e.g. BRAF K601E) is not specifically associated with malignant outcomes, with an approximately 40–80% probability of cancer or NIFTP." (PMID 35247035, 2022). "BRAF-mutation-mediated MAPK pathway downstream was often constitutively activated and led to cancer cell differentiation, proliferation, angiogenesis, and anti-apoptosis, suggesting targeting the BRAF pathway might inhibit HCC progression in the future." (PMID 36246599, 2022). "It is interesting to speculate this may be in part due to the alteration of over-activity in the Ras/BRAF/MEK/ERK and PI3KCA/AKT/mTOR pathways, which are commonly affected by gain-of-function mutations in various types of cancer and VAs." (PMID 35574555, 2022). "Therefore, LF-W271A/PA appears to preferentially target cancer cells relying on oncogenic BRAF–MEK–ERK signaling for survival." (PMID 35899070, 2022). "For instance, in cancers, the most noticeable oncogenes are BRAF and RAS." (PMID 36422095, 2022). "The presence of mutations or deletions of these genes suggest that decreased availability and function of the resulting proteins may be essential for BRAF mutant cancers both in vitro and in vivo." (PMID 36295658, 2022). "As our potentially lead drug candidates having lower toxicities profile so it could be provided an opportunity to develop lower toxic drug for the researcher and possible to treat BRAF overexpression related cancer." (PMID 36267655, 2022). "To test this hypothesis, we stably introduced a PIK3CA activating mutation into a BRAF-mutant PTC line and assessed the impact on a number of cancer related phenotypes in vitro and in vivo." (PMID 35193694, 2022).
cancer (continued). "Based on this, we reasoned that induction of YAP-mediated transcriptional output by vemurafenib could drive or contribute to adaptive resistance of BRAF-mutant cancer cells to this treatment." (PMID 36476495, 2022). "Given that BRAF interacts with SPOP in an SBC motif-dependent manner, we further explored whether cancer-associated BRAF mutations that occur in the SBC motif would attenuate the SPOP-BRAF interaction and permit BRAF to evade SPOP-mediated ubiquitination." (PMID 36585710, 2022). "Additionally, we sought to demonstrate specificity of RSL3 for targeting BRAF/RAS addicted cancer cells by selecting TPC-1, a PTC cell line, that lacks RAS or BRAF mutations." (PMID 36371529, 2022). "We found BRAF mutation to be significantly associated with high RI values (Wilcox p-value THCA < 2e−16, SKCM 2e−3) suggesting BRAF to be a key driver of oncogenic RAS pathway activity in these two cancers." (PMID 36163168, 2022). "BRAF V600E mutation encodes a constitutively activated B-RAF serine/threonine kinase that leads to a chronic hyperactivation of the RAS/RAF/MEK/ERK signaling pathway, driving oncogenesis in about 7% of human cancers." (PMID 35757402, 2022). "Furthermore, the most invasive cancer cells, particularly the oncogenic BRAF-mutant/MAPK-driven cancers, are the most sensitive to FC101′s anti-cancer activity." (PMID 36428475, 2022). "Our findings show BRAF V600 status plays an important role in regulating immunomodulatory lipid profiles and lipid trafficking, which may inform future therapy across cancers." (PMID 35565240, 2022). "SMAD4 mutations show a higher prevalence in BRAF/PIK3CA double mutant cancers of the TCGA cohort but not in cancers with BRAF mutations without PIK3CA mutations." (PMID 36079062, 2022). "Almost 200 BRAF mutants have been identified in various human cancers." (PMID 35585049, 2022). "Approximately 30% and 8% of all cancer types are related to KRAS and BRAF mutations, respectively." (PMID 35163468, 2022). "For all investigated cancer types, the author observed that mutations in upstream components of the MAPK/ERK signaling pathway, namely EGFR and RAS family proteins, co-occur much less frequently than expected with oncogenic mutations in BRAF." (PMID 36275468, 2022). "Nowadays, single or combination treatments of encorafenib have been explored in various BRAF mutant cancers, such as SKCM, PAAD, LUAD, COADREAD, THCA, and other advanced solid tumors in a clinical trial (NCT05003622; NCT04390243; NCT05195632; NCT04673955; NCT04061980; NCT03973918)." (PMID 35910024, 2022). "BRAF mutant cancers were located almost exclusively in the colon and rarely in the rectum." (PMID 36079062, 2022). "Increased reporting of CVAEs in clinical trials and further research into the mechanisms underlying these cardiotoxic effects ought to provide important information to allow optimal anti-cancer utility of BRAF and MEK inhibitors while minimizing potential cardiovascular adverse effects." (PMID 35492830, 2022). "Therefore this study aimed to identify potentially lead compounds that can target and block the expression of BRAF and subsequently inhibit the cancer." (PMID 36267655, 2022). "Therefore, the clinical treatment defects of these inhibitors for BRAF V600E positive cancer need to be further studied." (PMID 35748101, 2022). "The author speculates that these variants of unknown significance in these cancer types are passenger mutations and that the frequency of oncogenic and potentially targetable BRAF alterations in this cancer types is very low." (PMID 36275468, 2022). "We further analyzed the correlation between BRAF expression and pathological stages in pan-cancer." (PMID 35910024, 2022).
cancer (continued). "CRAF is important in maintaining activation of the MAPK pathway in RAS-mutated cancers because ERK1/2 has a negative feedback action through the phosphorylation of BRAF, which causes its inhibition." (PMID 35158973, 2022). "Therefore, we searched the methylation profiles of BRAF and its downstream genes in TCGA cancers by using the GSCALite database." (PMID 35910024, 2022). "This is reminiscent of the paradoxical MAPK activation observed BRAF-selective kinase inhibitors in BRAF-mut cancer models, whereby a kinase-inhibited BRAF protein is still able to form complexes with CRAF or yet unidentified interactors and paradoxically activate MEK and ERK downstream." (PMID 35719951, 2022). "Pan-cancer therapies, such as larotrectinib and entrectinib for NTRK rearrangement tumors, and dabrafenib combined with trametinib for treating BRAF V600E-mutated patients, could also have promising efficacy against BTC." (PMID 36072793, 2022). "Interestingly, the amount of HGF detected in the vem + pic group (11.4 ± 0.9 pg mL−1) significantly decreased by the cancer‐inhibiting effect of the BRAF/PI3K inhibitor." (PMID 36026581, 2022). "The eighth edition of the AJCC Cancer Staging System is focused on the individual treatment and prognostic factors of CRC based on molecular biomarkers, such as BRAF, KRAS, and NRAS that are associated with chromosomal instability, mismatch repair, and microsatellite instability." (PMID 36142151, 2022). "In addition, cancer-related mutations were found in P in 18 genes, including SMAD4 (11.9%), PIK3CA (11.9%), FBXW7 (9.5%), PTEN (7.1%), and BRAF (7.1%)." (PMID 35892888, 2022). "In this analysis, the distribution patterns of gene fusions involving BRAF varied in pan-cancer." (PMID 35910024, 2022). "Although BRAF-selective inhibitors block ERK signaling in tumors with BRAF mutation, they paradoxically activate ERK signaling and accelerate the growth of tumors with wild-type (WT) BRAF or with RAS mutations, thereby limiting the usefulness of BRAF inhibitors as a cancer therapy." (PMID 35585049, 2022). "The current results showed that the ZINC70454679, ZINC253500968, ZINC106887736, and ZINC107434492 compounds may be able to work against several cancers through targeting the BRAF overexpressed gene." (PMID 36267655, 2022). "The methodology described in this study may help guide clinical decisions in prescribing BRAF inhibitors and can be generalizable and applied to other cancers and targeted therapies." (PMID 35044091, 2022). "BRAF V600E and BRAF D594A are known mutations in various cancer types but their functional impact on liver cells is not defined." (PMID 35163468, 2022). "Unlike the high mutation rates of RAS, BRAF, and others genes in cancer cells, acquired mutations in ERK have thus far been virtually absent in cancer cells." (PMID 35401195, 2022). "The BRAF mutation, identified in ~80% of canine UC cases, results in inappropriate activation of the MAPK pathway with consequent abnormal proliferation and differentiation of cancers, including human and canine UC." (PMID 36072391, 2022). "Moreover, the combination with SHP2 inhibitors offers an appealing approach to treat both RTK-activated and KRAS/BRAF-mutant cancers." (PMID 35462913, 2022). "The predominantly mutated genes involved in this pathway, i.e., KRAS, BRAF and NF1, were found mutated in 26.05%, 17.06% and 13.06% of RTK-RAS perturbed cases respectively, while additional mutations in all cancer-related receptor tyrosine kinase-encoding genes represented 33.2% of all mutations." (PMID 35158934, 2022). "The mutant BRAF is therefore regarded as a drug target in cancer treatment." (PMID 36430869, 2022). "Then, we searched for NSCLC patients harboring these alterations in the cancer bioportal and in POPLAR and OAK trials using patient-level data, to investigate clinical and genomic differences associated with each BRAF functional class and the prognostic impact of BRAF non-V600 mutations." (PMID 35884534, 2022).